RN7SL41P (RNA, 7SL, cytoplasmic 41, pseudogene)
Gene: Miscellaneous RNA gene on chromosome 8 (80,204,606 to 80,204,902, forward strand). Ensembl gene ENSG00000241550.
Homologues: Orthologues: chimpanzee Metazoa_SRP (99% identical), macaque Metazoa_SRP (93% identical). Paralogues in human: RN7SL378P (80% identical), RN7SL1 (80% identical), RN7SL448P (79% identical), RN7SL2 (79% identical), RN7SL3 (79% identical), RN7SL868P (78% identical), RN7SL44P (78% identical), RN7SL126P (78% identical), RN7SL664P (78% identical), RN7SL803P (78% identical), RN7SL91P (78% identical), RN7SL230P (77% identical), and 701 more.